POLR3B (RNA polymerase III subunit B)
Diseases named in the same sentence as POLR3B in open-access papers (continued):
Sharing a sentence is not in itself a finding about the gene and the disease.
Wiedemann-Rautenstrauch syndrome (2 papers, 2021 to 2023). Wiedemann-Rautenstrauch syndrome is a very rare disorder with features of premature aging recognizable at birth, decreased subcutaneous fat, hypotrichosis, relative macrocephaly and dysmorphism. "Wiedemann-Rautenstrauch syndrome (neonatal progeroid syndrome) is an ultra-orphan disease from the group of premature aging syndromes with an autosomal recessive type of inheritance associated with mutations in the POLR3A, POLR3B, and POLR3GL genes encoding RNA polymerase III." (PMID 38796765, 2023).
4H leukodystrophy (1 paper, 2022). "4H leukodystrophy, one of POLR3-related leukodystrophy, is a rare hereditary brain white matter disease caused by the pathogenic biallelic variations in POLR3A, POLR3B, or POLR1C." (PMID 36042647, 2022).
Anosmia (1 paper, 2020). An inability to perceive odors. "PCSK1 and POLR3B are associated with normosmic CHH, but FGF17 mutations are associated with KS and anosmia, which implies a role during early GnRH neuron migration from the olfactory placodes as well." (PMID 31996360, 2020).
cataract (1 paper, 2017). Partial or complete opacity of the crystalline lens of one or both eyes that decreases visual acuity and eventually results in blindness. "The two patients we investigated with mutations in POLR3B genes showed diffuse hypomyelination of the cerebral and cerebellar white matter, hypodontia, and cataracts." (PMID 26478204, 2017). "Furthermore, as our patients are hypothesized to have mutations in two different genes, it is unclear whether the cataracts are caused by the POLR3B mutations or are rather caused by the second gene mutation(s) leading to PMG, microcephaly, and dysmorphic features." (PMID 26478204, 2017).
Epileptic seizures (1 paper, 2020). "Epileptic seizures were also present in families with NAGLU, SLC5A2, POLR3B, and VPS13A mutations, and behavioral and psychiatric symptoms were observed in a family with POLR3B mutations (Fam 03)." (PMID 31969655, 2020).
glioma (1 paper, 2015). A benign or malignant brain and spinal cord tumor that arises from glial cells (astrocytes, oligodendrocytes, ependymal cells). "Collectively POLR3B, ETFA, VTI1A, ZBTB16 and PHLDA1 are altered in 8% (22/286) of LGG as compared with 3% (8/273) of GBM (P=0.014) providing support for these genes having a role in glioma tumorigenesis." (PMID 26424050, 2015).
ovarian carcinoma (1 paper, 2024). A malignant neoplasm originating from the surface ovarian epithelium. "This investigation showcased a comprehensive genome-wide methylation profile of epithelial ovarian cancer (EOC) and identified six hypermethylated/downregulated genes, (POLR3B, PLXND1, GIGYF2, CRKL, STK4, and BMP2) as potential diagnostic targets." (PMID 38627856, 2024). "POLR3B and GIGYF2, identified as novel hypermethylated genes, might serve as promising biomarkers for diagnosing and predicting the prognosis of ovarian cancer." (PMID 38627856, 2024). "Interestingly we observed Non-CpG site methylation in the case of POLR3B and CRKL which was statistically significant in discriminating ovarian cancer samples from normal controls." (PMID 38627856, 2024).
proteinopathies (1 paper, 2021). "Alternatively, it is thought that mutations of RNA polymerase III subunit A (POLR3A) or RNA polymerase III subunit B (POLR3B) may induce aggregation of POLR3A and POLR3B proteins, leading to proteopathies (also called proteinopathies) associated with gain of function in POLR3A or POLR3B mutants." (PMID 33535532, 2021).
Tics (1 paper, 2021). Repeated, individually recognizable, intermittent movements or movement fragments that are almost always briefly suppressible and are usually associated with awareness of an urge to perform the movement. "Despite the wide range of the clinical manifestations of POLR3B mutations, tics are not considered one of them." (PMID 34389898, 2021).
viral infection (1 paper, 2015). "A viral infection is envisioned to interact with predisposition networks which include counterpart proteins in various downstream stages (including in the current data set: FOS, ELAVL1, NFkB1, POLR3B, and others at different cellular compartments and stages of the tumorigenesis)." (PMID 26442106, 2015).
cancer (2 papers, 2015 to 2018). A tumor composed of atypical neoplastic, often pleomorphic cells that invade other tissues.
peripheral neuropathy (1 paper, 2021). A disorder affecting the peripheral nervous system. "To date, only one study has reported the demyelinating peripheral neuropathy phenotype caused by heterozygous POLR3B variants." (PMID 34666706, 2021). "Notably, five of the six patients exhibited predominant demyelinating sensory and motor neuropathy, which unveiled for the first time a demyelinating peripheral neuropathy phenotype caused by POLR3B variants." (PMID 34666706, 2021).
POLR3B also shares sentences with these, for which no sentence is quoted: Hypodontia (3 papers); Intellectual disability (3); cerebellar ataxia (2); epilepsy (2); tumor (2); amyotrophic lateral sclerosis (1); bladder cancer (1); Charcot-Marie-Tooth disease (1); demyelinating (1); glioblastoma (1); hyperopia (1); hypocortisolism (1); Leukoencephalopathy (1); lung adenocarcinoma (1); microcephaly (1); neurodegenerative disease (1); polymicrogyria (1); Primary amenorrhea (1); progeria (1); Spasticity (1).